HSPA5 (heat shock protein family A (Hsp70) member 5)
Diseases named in the same sentence as HSPA5 in open-access papers (continued):
Sharing a sentence is not in itself a finding about the gene and the disease.
colorectal cancer (60 papers, 2010 to 2026). A primary or metastatic malignant neoplasm that affects the colon or rectum. "The result indicated that STAT3 was positively associated with HSPA5 in patients with colorectal cancer (r2 = 0.12, p < 0.0001)." (PMID 33023006, 2020). "Lastly, our results suggested FOXM1 facilitated the activities of MMP2 and 9 associated with HSPA5 in colorectal cancer cells." (PMID 27034162, 2016). "Lastly, our results suggested FOXM1 facilitated the activities and expressions of MMP2 and 9 associated with cell-surface HSPA5 in colorectal cancer cells." (PMID 27034162, 2016). "According to the dbCPCO database, only one of the SNPs identified in this study – HSPA5.rs12009 – was investigated in relation to colorectal cancer outcomes in a stage II-III patient cohort." (PMID 36998434, 2023). "In conclusion, a STAT3-miR-30a-5p-HSPA5 axis was observed against regorafenib-mediated apoptosis in colorectal cancer tumorspheres." (PMID 33023006, 2020). "Consistent with previous studies, we showed that the HSPA5 increased MMP2 mRNA production involved in JNK activities in colorectal cancer cells." (PMID 27034162, 2016). "Here, we found that enhancement of migration and invasion by FOXM1 was significantly attenuated by depletion of HSPA5 in colorectal cancer cell." (PMID 27034162, 2016). "In this study, a significant positive correlation of FOXM1 with HSPA5 mRNA expression was observed in colorectal cancer specimens." (PMID 27034162, 2016). "We observed statistically significant positive correlations between FOXM1 and HSPA5 mRNA expression in colorectal cancer and adjacent normal tissue specimens (for tumor tissue: r = 0.445, P = 8.92×10−6; for normal tissue: r = 0.571, P = 5.28×10−9)." (PMID 27034162, 2016). "Previous studies have shown that cell-surface HSPA5 increased colorectal cancer cell migration and invasion." (PMID 27034162, 2016). "Increased expression of HSPA5 protein has been found in several types of cancer including colorectal cancer." (PMID 27034162, 2016). "FOXM1 mRNA level was firstly found to positively correlate with HSPA5 in colorectal cancer and adjacent normal tissue samples." (PMID 27034162, 2016). "We ectopically introduced siRNA against HSPA5 to FOXM1-overexpressed colorectal cancer cells respectively." (PMID 27034162, 2016). "After normalization to cell viability, blocking cell-surface HSPA5 with antibody significantly diminished colorectal cancer cell migration." (PMID 27034162, 2016). "Here, HSPA5 also was shown to be frequently highly expressed in colorectal cancer tissue, whereas lower levels HSPA5 were found in normal tissue." (PMID 27034162, 2016). "All above results indicated that FOXM1 binds to and activates HSPA5 promoter in colorectal cancer cells." (PMID 27034162, 2016). "To investigate the relationship between FOXM1 with ER stress in colorectal cancer, we first analyzed HSPA5, spliced XBP1 and FOXM1 mRNA expression by qRT-PCR in colorectal cancer specimens." (PMID 27034162, 2016). "FoxM1 increases the invasion and migration of colorectal cancer by binding to the HSPA5 promoter." (PMID 32035486, 2020). "Furthermore, in colorectal cancer, curcumin can modulate gene expression of HSPA5, SEC61B, G6PD, HMOX1, and PDE3B, affecting essential pathways like DNA replication or the cell cycle." (PMID 31744117, 2019). "To elucidate the relationship between FOXM1 and HSPA5 expression in colorectal cancer cells, we used two siRNAs against FOXM1 as well as FOXM1b or FOXM1c lentiviral high-expression vectors to transfect two colorectal cancer cell lines, namely SW1116 and LOVO cells." (PMID 27034162, 2016). "Notably, HSPA5 expression in cancer specimens is negatively correlated with lymphatic invasion in colorectal cancer patients." (PMID 27034162, 2016). "Additionally, we found statistically significant positive correlations between spliced XBP1 and HSPA5 mRNA expression in colorectal cancer (r = 0.443, P = 3.12×10−6)." (PMID 27034162, 2016).
colorectal cancer (continued). "Moreover, we found the mRNA expression of HSPA5 in colorectal cancer cells was induced by both FOXM1b and c." (PMID 27034162, 2016). "Furthermore, FOXM1 triggered colorectal cancer cell migration and invasion was involved in activities of cell-surface HSPA5." (PMID 27034162, 2016). "FOXM1 mRNA levels were found to positively correlate with HSPA5 in colorectal cancer." (PMID 27034162, 2016). "Furthermore, FOXM1 triggered colorectal cancer cell migration and invasion were involved in activities of cell-surface HSPA5." (PMID 27034162, 2016). "In addition, we found that enhancement of cell migration and invasion by FOXM1 was significantly attenuated by depletion of HSPA5 in colorectal cancer cell." (PMID 27034162, 2016). "Additionally, upregulation of HSPA5 also accelerates colorectal cancer cell migration and invasion." (PMID 27034162, 2016). "Hence, we detected whether cell-surface HSPA5 is required for colorectal cancer cell migration and invasion induced by FOXM1." (PMID 27034162, 2016). "Therefore, we investigated whether HSPA5 contributed colorectal cancer cells invasion and migration induced by FOXM1." (PMID 27034162, 2016). "However, HSPA5 positively correlated with spliced XBP1 mRNA in the colorectal cancer tissues." (PMID 27034162, 2016). "Additionally, HSPA5 also plays a major role in enhancing colorectal cancer cell migration." (PMID 27034162, 2016). "We next tested whether HSPA5 induced the expression of FOXM1 in colorectal cancer." (PMID 27034162, 2016). "Moreover, analysis of TCGA colorectal cancer data using the GEPIA2 online tool revealed that STK26 exhibits significant positive correlations with mRNA expression levels of ATF6 pathway downstream effectors (HSPA5, XBP1), clinically corroborating our experimental findings." (PMID 40869379, 2025). "Studies have proved that HSPA5 can bind to GPX4 and inhibit GPX4 protein degradation, thereby inhibiting ferroptosis in pancreatic ductal adenocarcinoma (PDAC) cells and colorectal cancer (CRC) cells." (PMID 36591279, 2022). "After normalization to cell viability, FOXM1 significantly enhanced cell migration and invasion, however depletion of HSPA5 using siRNA obviously attenuated cell migration and invasion induced by FOXM1 in colorectal cancer cells." (PMID 27034162, 2016). "Subsequently, in colorectal cancer cell lines, we showed that knocking down FOXM1 decreased HSPA5 expression, whereas overexpression of FOXM1 increased HSPA5 level." (PMID 27034162, 2016). "To exclude the possibility of transcriptional upregulation of both HSPA5 and FOXM1 induced by hypoxia in advanced colorectal cancer, we analyzed the correlation between FOXM1 and spliced XBP1 mRNA, an indicator of ER stress." (PMID 27034162, 2016). "We further demonstrated that the targeting of HSPA5 by HA15 significantly inhibited cell viability and increased apoptosis and prevented the formation of colorectal cancer HT29-derived tumorspheres, thus indicating that the STAT3-miR-30a-HSPA5 axis contributed to anti-apoptosis in CRC." (PMID 33023006, 2020). "Moreover, we observed statistically significantly positive correlations between FOXM1 and MMP2 mRNA expression, between HSPA5 and MMP2 in colorectal cancer tissue specimens." (PMID 27034162, 2016). "Moreover, statistically significant positive correlations between FOXM1 and MMP2 mRNA expression, between HSPA5 and MMP2 were found in colorectal cancer tissue specimens." (PMID 27034162, 2016). "In this study, to investigate whether endoplastic reticulum (ER) stress correlated with FOXM1 in colorectal cancer, we analysed the mRNA levels of FOXM1 and ER stress markers HSPA5 and spliced XBP1 by qRT-PCR." (PMID 27034162, 2016). "Moreover, we observed statistically significant positive correlations between FOXM1 and MMP2 mRNA expression (n = 92, r = 0.6001, P = 2.71×10−10), between HSPA5 and MMP2 (n = 92, r = 0.403, P = 6.89×10−5) in colorectal cancer tissue specimens." (PMID 27034162, 2016).
colorectal cancer (continued). "All above results pointed out FOXM1 correlated with HSPA5 in colorectal cancer was independent of hypoxia or ER stress by hypoxia." (PMID 27034162, 2016).
COVID-19 (57 papers, 2020 to 2025). A disease caused by infection with severe acute respiratory syndrome coronavirus 2. "Since cell surface HSPA5 expression is associated with cancer and COVID-19, antibody strategies represent exciting target therapeutics." (PMID 37275848, 2023). "For example, HSPA5 (heat shock protein family A (Hsp70) member 5) can play diverse functional roles in cell viability, proliferation, apoptosis, attachment, and innate and adaptive immunity regulation, which can lead to various diseases, including cancers and coronavirus disease 2019 (COVID-19)." (PMID 40429988, 2025). "Recent studies on COVID-19 have identified HSPA5 as a potential host–cell receptor for SARS-CoV-2, since lung tissue with high expression of HSPA5 seemed to be highly susceptible to invasion of the virus." (PMID 36835223, 2023). "Several altered proteins in the serum of COVID-19 positive asymptomatic donors (FGA, SERPINA1, THBS1) and moreover, in CACs treated with these serum factors (HSPA5, FN1), have been associated with platelet aggregation and coagulation problems." (PMID 35397534, 2022). "Thus, the downregulation of HSPA5 might be one cause for the more promising results of treating COVID-19 with Rem such as the Adaptive COVID-19 Treatment Trial (ACTT-1) found that patients receiving Rem treatment tend to profit from a significantly shorter time to recovery compared to placebo." (PMID 35686037, 2022). "Taken together, this study not only indicates the clinical significance of HSPA5 in COVID-19 disease and cancers, but also provides potential clues for further medical treatments and managements of COVID-19 patients." (PMID 33767597, 2021). "Additionally, it was reported that cs-HSPA5 is responsible for many infectious diseases, including mucormycosis, Japanese Encephalitis, and COVID-19, through different pathways or targets." (PMID 37275848, 2023). "Targeting HSPA5 expression by natural products may imply the significance in clinical for both anti-COVID-19 and anti-cancers in the future." (PMID 37275848, 2023). "Interestingly, proteins such as apolipoprotein H (APOH), C-type lectin domain family 3 member B (CLEC3B), and heat shock 70kDa protein 5 (HSPA5) also showed opposite trends between COVID-19 patients and CoronaVac immunized subjects." (PMID 35686122, 2022). "Collectively, this study may not only imply the clinical significance of the role of HSPA5 in COVID-19 disease and cancers, but also provide a potential clue for further medical treatments and managements of COVID-19 patients." (PMID 33767597, 2021). "Therefore, we could consider the potential of using HSPA5 inhibitors/antibodies for COVID-19 treatment." (PMID 37275848, 2023). "A decrease in HSPA5 expression may potentially prevent COVID-19, especially in cancer patients." (PMID 37275848, 2023). "Targeting HSPA5 may not only implies the significance in clinical for both anti-COVID-19 and anti-cancers but also provides an intriguing clue for medical treatments and management of cancer patients with COVID-19 in the future." (PMID 37275848, 2023). "Therefore, targeting HSPA5 expression by natural products may imply the significance in clinical for both anti-COVID-19 and anti-cancers in the future." (PMID 37275848, 2023). "Targeting HSPA5 may be potential in therapy for human diseases 7, 8 as well as COVID-19 9-11." (PMID 33767597, 2021). "However, the impacts of HSPA5 on SARS-CoV-2 susceptibility and the characterization of malignant cancer patients in the COVID-19 outbreaks are unknown." (PMID 33767597, 2021). "Understanding the HSPA5 expressions and localizations of entry proteins/receptors of SARS-CoV-2 in host tissues can give insights into COVID-19 therapeutics for reducing the spread of COVID-19, viral replication, disease pathology, and disease severity." (PMID 37275848, 2023). "Increased levels of S100A8, MKI67, HSPA5, LYZ, CTSD, and IGHG1 were observed in COVID-19 patients." (PMID 39026676, 2024).
COVID-19 (continued). "These proteins were connected in silico to several serum markers upregulated in critical COVID-19 patients, including the chaperone Heat shock protein HSPA5, also called glucose regulating protein 78 (GRP78), a glycoprotein upregulated as result of ER stress mediated by COVID-19 infection." (PMID 37063416, 2023). "On the cell surface, HSPA5/BiP/GRP78 can play diverse functional roles in cell viability, proliferation, apoptosis, attachments, and innate and adaptive immunity regulations, which lead to various diseases, including cancers and coronavirus disease 2019 (COVID-19)." (PMID 37275848, 2023).
glioblastoma (55 papers, 2012 to 2026). The most malignant astrocytic tumor (WHO grade IV). "HSPA5 was reported to determine the sensitivity of glioblastoma to UBA1 inhibition-induced UPR signaling and the death of cancer cells." (PMID 37275848, 2023). "Survival analysis revealed eight RBPs (PTRF, FNDC3B, SLC25A43, ZC3H12A, LRRFIP1, HSP90B1, HSPA5, and BNC2) are significantly associated with the survival of glioblastoma patients." (PMID 32272554, 2020).
ovarian carcinoma (53 papers, 2012 to 2025). A malignant neoplasm originating from the surface ovarian epithelium. "In patients with prostate or ovarian cancer, the extracellular expositions of HSPA5 lead to product autoantibodies, which possess the ability of HSPA5 targeting." (PMID 37275848, 2023). "HSPA5 inhibits the growth of epithelial ovarian cancer cells through G1 phase arrest." (PMID 34109184, 2021). "By screening 31 drugs with 110 targets, FNTA, HSPA5, NEU1, CCND1, CASP1, CASP3 were negatively correlated with ovarian cancer, and HMGCR, PLA2G4A, ITGAL, PTGS1, FNTB were positively correlated with ovarian cancer." (PMID 38651149, 2024). "By stabilizing HSPA5, deubiquitinase USP11 was said to promote the chemoresistance of ovarian cancer." (PMID 37275848, 2023). "In addition aspirin may inhibit several targets such as HSPA5, NEU1, CCND1, CASP1, CASP3, which are negatively correlated with ovarian cancer prognosis." (PMID 38651149, 2024). "Among them, FNTA, HSPA5, NEU1, CCND1, CASP1, CASP3 had a negative causal association with ovarian cancer development, and HMGCR, PLA2G4A, ITGAL, PTGS1, FNTB had a positive causal association with ovarian cancer development." (PMID 38651149, 2024). "Eight immune factors (IFT57, MAL, ANXA4, SCRN1, LTBR, KIFAP3, HSPA5, and LTN1) were positively correlated with poor prognosis of ovarian cancer, whereas six immune factors (PSMB9, FOXJ1, CTSH, MIF, CTSD, and PSMB8) were negatively correlated with poor prognosis of ovarian cancer." (PMID 34109184, 2021).
Hepatic steatosis (36 papers, 2011 to 2025). Steatosis is a term used to denote lipid accumulation within hepatocytes. "Studies using mouse models reported that loss of HSPA5 exacerbates fatty liver disease, while overexpression of HSPA5 reduces liver steatosis." (PMID 35906520, 2023). "Increased HSPA5 expression has been shown to protect against hepatic steatosis, whereas HSPA5 loss induces it." (PMID 30818824, 2019). "On the other side, thapsigargin was found to promote the phosphorylation of EIF2AK3, which was markedly reduced by overexpression of Hspa5 in hepatic steatosis in mice." (PMID 39000233, 2024). "Thus, Hspa5 downregulation in the livers of db/db mice would also be consistent with the enhanced development of hepatic steatosis in these mice and was not prevented in our hA-I-db/db mice." (PMID 30717414, 2019). "As the HSPA5 decrease in PCLSs is in line with observations in NAFLD/NASH patients, it might be interesting to study the relation between ER stress, UPR, and fatty liver disease in this PCLS model." (PMID 30818824, 2019).
Hyperglycemia (36 papers, 2013 to 2026). An increased concentration of glucose in the blood. "Grp78/HspA5 is overexpressed in patients with hyperglycaemia, DKA, and elevated serum iron; thus, antibodies, i.e., anti-Grp78 may be promising novel targets as it was shown to offer protection in a murine DKA model." (PMID 33143139, 2020).
myeloma (29 papers, 2013 to 2025). "Gene expression profiling of newly diagnosed myeloma patient tumors further correlated the hyperexpression of GRP78-encoding HSPA5 with reduced clinical response to bortezomib." (PMID 38067336, 2023). "In a phase 1 trial (NCT01727778), the monoclonal immunoglobulin M antibody PAT-SM6 targeting the cell surface GRP78/BiP (HSPA5) in subjects with relapsed or refractory multiple myeloma demonstrated good tolerability." (PMID 41301006, 2025). "Myeloma cells were transfected with shRNA to knockdown HSPA5, treated with bortezomib and the effect on cleavage of PARP and caspase determined by western blot." (PMID 25605012, 2015).
liver cancer (27 papers, 2012 to 2025). An epithelial or non-epithelial malignant neoplasm that arises from the liver. "For example, the CD5-like (CD5L) promotes liver cancer cell proliferation and anti-apoptotic responses by binding to HSPA5/GRP78." (PMID 37156995, 2023). "HSPA5 is regulated by CD5L and promotes the proliferation of liver cancer cells, playing an antiapoptotic role." (PMID 36982218, 2023). "Thus antibodies can direct against both the N and C-terminus of HSPA5, majorly affecting the binding of the SARS-CoV-2 to the cell surface and its infectivity to liver cancer." (PMID 37275848, 2023).
endometrial cancer (25 papers, 2014 to 2025). Primary or metastatic malignant neoplasm involving the endometrium (mucous membrane that lines the endometrial cavity). "PKM2 and HSPA5 were significantly increased in high-risk endometrial cancer, regarding low-risk endometrial cancer and normal endometrium, suggesting they are potentially predicting risk biomarkers for endometrial cancer." (PMID 39194522, 2024). "The expression of HSPA5 was reported to be higher in high-risk endometrial cancer than in low-risk endometrial cancer and normal endometrium, which suggested that HSPA5 was also associated with higher malignant degree and poor prognosis of endometrial cancer." (PMID 35847989, 2022). "The glucose regulated protein 78 (Grp78), Hsc70, and mortalin proteins encoded by the heat shock protein A (HSPA) 5, 8, and 9 genes, respectively, have the highest mutation frequencies in endometrial cancer compared to other cancers evaluated in The Cancer Genome Atlas (TCGA)." (PMID 34066052, 2021). "In endometrial cancer, two members of the heat shock proteins (HSP) family, HSPA5 and HSPA8, were proposed as good markers for diagnosis and prognosis." (PMID 39194522, 2024).
neuroblastoma (25 papers, 2010 to 2025). Neuroblastoma (NB) is the most common solid, extracranial childhood tumor. "On the contrary, another report demonstrated that exposure to SiNPs increased the expression of HSPA5 and other markers of unfolded protein response proteins in spermatocyte cells and the human neuroblastoma cell line." (PMID 35906520, 2023). "HSPA5, HERPUD1, and CLU expression increased in vivo and cultured neuroblastoma cells." (PMID 35984750, 2022).
breast tumors (21 papers, 2008 to 2025). "Indeed, several studies clearly demonstrated by immunohistochemistry and proteomic analyses that human breast tumors express much higher levels of HSPA5 than normal tissue." (PMID 34943954, 2021).